IL32 (interleukin 32)
Diseases named in the same sentence as IL32 in open-access papers (continued):
Sharing a sentence is not in itself a finding about the gene and the disease.
breast carcinoma (continued). "The “data analysis tools” available on GEO were used to analyze the GDS2250 breast cancer dataset and IL32 was found differentially expressed in the basal-like patient samples." (PMID 25100201, 2014). "For example, the IL32 protein secreted by CAFs binds to integrin β3 on the surface of breast cancer cells, thereby activating the downstream p38MAPK pathway and enhancing the invasion and metastasis of breast cancer cells." (PMID 37978384, 2023). "Hypoxia-induced ROS have been shown to increase IL-32 expression in breast cancer cells." (PMID 37686029, 2023). "Though the over-expression of IL-32 was found in gastric cancer, lung cancer, breast cancer and esophageal cancer, the specific roles of IL-32 in ESCC cells remains largely unknown." (PMID 35428295, 2022). "However this study is the first to show differential IL32 expression in MF fibroblasts compared to normal fibroblasts, which resembles a recent study where IL-32 was found to be abundantly expressed in CAFs in the breast cancer TME." (PMID 33941102, 2021). "In human melanoma, colon cancer, breast cancer, and other cancer types, IL-32 can be induced by tumor necrosis factor (TNFα and IFNγ to inhibit cancer development, and its high expression may be related to the therapeutic effect of PD1." (PMID 34414188, 2021). "Compared to other groups, slightly higher levels of IL32 gene were detected in HER2 breast cancers." (PMID 28966727, 2017). "IL-32 promotes angiogenesis and breast cancer cell proliferation." (PMID 27589563, 2016). "Indeed, the current study found that in culture IL-32 seems to enhance survival of breast cancer cells in a glucose-withdrawn environment." (PMID 25435980, 2015). "Future studies, which investigate the combination of IL-32 silencing and chemotherapy drugs for breast cancer treatment may be useful." (PMID 25435980, 2015). "IL32 is a cytokine, and immune-related genes and cell types are proving to be important tools in understanding the contribution of the tumor’s microenvironment in breast cancer pathogenesis." (PMID 25100201, 2014). "In summary, IL-32 may represent a useful therapeutic target for human breast cancer." (PMID 25435980, 2015). "Therefore IL-32 may be a novel therapeutic target for breast cancer, and potentially other types of cancer as well." (PMID 25435980, 2015). "The knockdown of IL-32, β3 integrin, and blockade of MAPK signaling reduced the invasiveness of breast cancer." (PMID 38258051, 2023). "For example, interleukin-32 (IL-32) interacts with integrin-β3 on cancer cells and activates p38 MAPK pathway, which promotes EMT and invasion in breast cancer." (PMID 34572947, 2021). "We confirmed the therapeutic efficacy of IL-32 in subcutaneously injected MC38 colon adenocarcinomas and orthotopically inoculated 4T1 mammary carcinomas." (PMID 32841222, 2020). "IL-32 is mainly derived from CAFs, whereas ITGB3 is upregulated during EMT in breast cancer cells." (PMID 37217855, 2023). "Of note, regardless of breast cancer, colorectal cancer, and bladder cancer, the expression of IL-32 has been identified in several tumor tissues." (PMID 35069212, 2021). "However, to the best of our knowledge, the direct effect of IL-32 on breast cancer cell growth has not yet been investigated." (PMID 25435980, 2015). "In addition, rodents lack the expression of IL-32; hence, the effects of IL-32 on breast cancer xenografts in nude mice have not been studied." (PMID 25435980, 2015). "For this current study, we observed the IL32 gene differentially expressed in basal-like and TNBC, performed preliminary analysis of gene expression in particular cell lines and tissue samples, and suggested it be examined further for its role in breast cancers." (PMID 25100201, 2014). "In an earlier study, we identified Interleukin 32 (IL32) as differentially expressed in TNBC compared to non-tumor and luminal breast cancer cell lines and patient samples." (PMID 28966727, 2017).
gastric cancer (25 papers, 2014 to 2025). A primary or metastatic malignant neoplasm involving the stomach. "IL-32 was highly associated with gastric cancer progression mainly due to its stimulation of cell elongation and in turn enhanced invasion and migration." (PMID 35281008, 2022). "Then, modulated by AKT, β-catenin and HIF-1α signaling pathways, IL32 was closely associated with metastasis of gastric cancer." (PMID 34116604, 2021). "While IL32 has context-dependent immunological roles, its association with the non-responder phenotype in our study suggests it may contribute to resistance against treatments in gastric cancer." (PMID 40723289, 2025). "In the context of this malignancy, up-regulation of IL-32 is not only associated with H. pylori infection, but also can be used as prognostic marker for gastric cancer patients since its expression is increased in human gastritis and gastric cancer cells, compared to normal cells." (PMID 26395996, 2016). "VEGF expression was found to be correlated with the expression of IL-32 in cancers with invasion and migration ability such as lung, breast, and gastric cancers although it was indicated that IL-32γ pro angiogenetic activity was not mediated by VEGF." (PMID 35281008, 2022). "It was noted that the expressed IL-32 isoforms were α, β, and γ in gastric cancer samples, while the dominant isoform was IL-32β." (PMID 35281008, 2022). "For example, IL32 contributes to gastric cancer progression by increasing the metastatic potential resulting from AKT, β-catenin and HIF-1α activation." (PMID 32308549, 2020). "Within patients with diffuse type of gastric cancer, IL-32 score 2 was recorded for 40% of patients, while IL-32 score 2 was recorded for 3% of patients with intestinal type of gastric cancer." (PMID 30402092, 2018). "It has been reported that systemic concentration of IL-32 is significantly increased in patients with gastric cancer in comparison to healthy control." (PMID 30402092, 2018). "The aim of the study was to determine the expression of IL-32, proinflammatory and angiogenic mediators, in patients with diffuse and intestinal gastric cancer and the relationship with clinicopathological aspects." (PMID 30402092, 2018). "Our results revealed higher IL-32 expression in patients with diffuse type of gastric cancer in comparison to intestinal form of tumor." (PMID 30402092, 2018). "IL-32 expression was significantly lower in tissue samples from patients with diffuse type of gastric cancer that is also a severe and more progressive form (TNM stages III and IV, poor histological differentiation, and higher nuclear grade III)." (PMID 30402092, 2018). "Earlier study also confirmed that expression of IL-32 in patients with gastric cancer positively correlated with poor prognosis." (PMID 30402092, 2018). "In order to investigate potential biological role of IL-32 in obvious difference in severeness of diffuse form of gastric cancer in comparison to intestinal form, we have analyzed the expression of IL-32 in tumor tissue." (PMID 30402092, 2018). "Studies in solid tumors, such as gastric cancers, pancreatic cancers and renal carcinomas, have found high expression of IL-32, suggesting that this cytokine is an independent prognostic factor." (PMID 29190960, 2017). "In human stomach cancer and pancreatic cancer patients, IL-32 is highly expressed compared with healthy individuals." (PMID 29190960, 2017). "Tsai and co-workers also reported that high expression of IL-32 in gastric cancer was positively correlated with tumor metastasis and poor prognosis." (PMID 29190960, 2017). "As in the case of lung cancer, pro-tumorigenic properties of IL-32 were also confirmed for gastric cancer." (PMID 26395996, 2016). "IL-32 has pro-cancer effects in most lung cancers and is also used as a prognostic marker for gastric cancer." (PMID 27589563, 2016).
gastric cancer (continued). "In the current review, we have highlighted the involvement of IL-32 in gastric cancer, gastric inflammation, and chronic rhinosinusitis." (PMID 27143819, 2016). "Average serum level of IL-32 was found significantly higher in patients of stomach cancer (189 pg/mL, n = 16) compared to healthy control (109 pg/mL, n = 12)." (PMID 27143819, 2016). "For example, gastric cancer cells secrete IL-8 which in the presence of a high level of IL-32 has been reported in mucosa of gastric cancer compared to nontumor mucosa." (PMID 27143819, 2016). "Oppositely, overexpression of IL32 has been shown to be an independent prognostic marker for gastric cancer." (PMID 25100201, 2014). "CAF-exosomes promoted cell migration and invasion of gastric cancer through the IL-32/ESR1 pathway." (PMID 39735680, 2025). "Based on the report, IL-32 is highly expressed in patients with pancreatic cancer or gastric cancer and IL-32 has pro-cancer effects that inhibit apoptosis, stimulate DNA synthesis in the proliferation of cancer cells, and increase invasion associated with tumor progression and metastasis." (PMID 38675491, 2024). "Mechanistically, IL-32 has been demonstrated to promote changes in gastric cancer cell morphology, facilitating their migration, and to enhance their potential for invasiveness by upregulating the expression of matrix metalloproteinases (MMP)-2 and 9, VEGF-A, and IL-8 via HIF-1α activation." (PMID 33020452, 2020). "This emphasizes on unrecognized role of IL-32 in biology of diffuse type of gastric cancer." (PMID 30402092, 2018). "Moreover, Spearman's correlation test revealed that higher expression of IL-32 negatively correlates with more severe diffuse form of gastric cancer (r = −0.367; p = 0.002)." (PMID 30402092, 2018). "Downregulated expression of IL-32 in tumor tissue of patients with diffuse type of gastric cancer may implicate on its role in limiting ongoing proinflammatory and proangiogenic processes." (PMID 30402092, 2018). "In conclusion, IL-32 is a key modulator in the pathogenesis of various clinical problems which is mostly induced by IL-8 and enhances the severity of gastric inflammation, gastric cancer, and chronic rhino sinusitis." (PMID 27143819, 2016). "Taking into the account previous studies showing an antagonistic activity of LL-37 against IL-32 in gastric cancer cells, it might be assumed that similar relationship function during lung cancer development." (PMID 26395996, 2016). "It has been suggested that IL-32-positive expression was frequently associated with lymph node metastasis in gastric cancer and lung cancer." (PMID 25889282, 2015). "In addition, IL-32 expression has been identified as a marker of gastric cancer." (PMID 25726525, 2015). "The data revealed a gene expression pattern in EBV-positive gastric cancer, highlighting immune response, inflammation, and cell proliferation genes (e.g., GBP4, ICAM1, IL32, TNFSF10)." (PMID 40110195, 2025). "Recently, several studies have indicated that IL-32 induces the expression of MMP-2 and MMP-9 in gastric cancer and lung adenocarcinoma." (PMID 27589563, 2016). "On the one hand, IL-32 was reported to augment cancer progression, proliferation, invasion, and metastasis in many tumors including acute myeloid leukemia (AML), hepatocellular carcinoma (HCC), and breast, lung, colon, pancreatic, and gastric cancers." (PMID 35281008, 2022). "The role of IL-32 gastric cancer seems to be unequivocally negative." (PMID 33020452, 2020). "Taken together, dysregulated RELB, IL-32, and SLC7A11 may mediate inflammatory responses, oxidative stress levels or cellular energy metabolism to potentiate the ability of H. pylori to induce gastric carcinoma." (PMID 32457731, 2020).
inflammatory bowel disease (24 papers, 2011 to 2025). A spectrum of small and large bowel inflammatory diseases of unknown etiology. "For these reasons, IL-32 has been recognized as a proinflammatory cytokine, and has been implicated in inflammatory disorders such as RA and inflammatory bowel disease." (PMID 23148681, 2012). "Although IL-32 has been associated with the pathophysiology of inflammatory bowel disease, evidence suggests that it may also play an immunoregulatory role in the progression of disease." (PMID 36246229, 2022). "IL-32 is known to be upregulated in multiple inflammatory conditions associated with increased risk for the development of cardiovascular diseases, such with chronic viral and bacterial infections, inflammatory bowel disease and chronic obstructive pulmonary disease." (PMID 36992409, 2023). "Consistently, IL-32 involvement has been documented in infectious diseases, chronic inflammatory conditions, including gastritis, inflammatory bowel disease, and cancer." (PMID 40110195, 2025). "IL-32 is involved in several chronic inflammatory diseases, including chronic rhinosinusitis, ankylosing spondylitis, and inflammatory bowel diseases." (PMID 36428561, 2022). "IL-32 showed a pro-inflammatory effect in various diseases such as arthritis, Crohn’s disease, and inflammatory bowel disease." (PMID 30486830, 2018). "The overexpression of IL-32 in a number of diseases including asthma, inflammatory bowel disease (IBD) and RA has been reported to be induced by IL-18." (PMID 25626592, 2015). "Recently, the expression of IL-32 was demonstrated in Mycobacterium tuberculosis infections, inflammatory bowel disease and influenza A virus infection, in addition to that in autoimmune disease." (PMID 23148681, 2012). "Moreover, the interaction between inflammation and hypoxia in the regulation of IL-32 further support the established bidirectional relationship between the two, manifesting in diseases such as inflammatory bowel disease." (PMID 37572852, 2023).
melanoma (22 papers, 2014 to 2025). A malignant, usually aggressive tumor composed of atypical, neoplastic melanocytes. "In melanoma, increased IL-32 expression was also associated with higher levels of cDC1 and improved overall survival." (PMID 32841222, 2020). "In light of the impact of a proinflammatory microenvironment on melanoma differentiation, as well as the association between IL32 and dedifferentiation in melanoma cell lines, we investigated if this phenomenon was also present in the TCGA dataset." (PMID 30953519, 2019). "Consequently, IL-32 injections reduced the growth of various syngeneic tumors, and IL-32 expression was associated with prolonged overall survival of patients with melanoma." (PMID 32841222, 2020). "Thus, we evaluated the biology underlying IL32 expression in the context of melanoma both in cell lines and in melanoma tumor samples." (PMID 30953519, 2019). "In contrast, IL32 induces ICI-resistant melanoma by activating DCs to secrete CCL5-primed CD8+ TILs." (PMID 38343549, 2024). "Different studies have found that IL-32 plays a role in both, the development, and the induction of an immune response in melanoma and cutaneous T-cell lymphoma (CTCL)." (PMID 37727785, 2023). "While its role in some cancers was controversial, several reports highlighted a possible role of IL-32 in inhibiting cell proliferation in colon, prostate, and melanoma malignant cells." (PMID 36845147, 2023). "IL-32 treatment reduced tumor growth and rendered immune checkpoint blockade-resistant melanoma responsive to anti–PD-1 therapy." (PMID 35903675, 2022). "In vivo research shows that it increases lung metastasis in mice with melanoma, so IL-32 also acts as a pro-invasive molecule." (PMID 34068679, 2021). "In order to examine the effects of IL-32 on the expression of over 500 immune-related genes in both human melanoma and immune cell subsets, we used the NanoString Human Immunology Panel V2." (PMID 32841222, 2020). "Given our findings showing a beneficial role of IL-32 in human melanoma, we investigated the efficacy of IL-32 as a tumor immunotherapy in mice." (PMID 32841222, 2020). "While additional studies are required to validate IL-32 as a predictive or prognostic biomarker and to translate IL-32 as a tumor immunotherapy to the clinic, the therapeutic efficacy of this cytokine for melanoma treatment has been demonstrated in this study." (PMID 32841222, 2020). "Subsequently, we analyzed IL-32 gene expression in biopsies from patients with melanoma before treatment with anti–PD-1 (nivolumab or pembrolizumab)." (PMID 32841222, 2020). "Together, our data suggests that in human melanoma IL-32 is primarily expressed in lymphocytes and enhances the activation of intratumoral myeloid cells in a paracrine fashion." (PMID 32841222, 2020). "Due to the indispensable role of cDC1 in cancer immunity we assessed the relationship between IL-32 and cDC1 in human melanoma." (PMID 32841222, 2020). "IL-32 expression positively correlates with myeloid markers, mature DC, and increased overall survival in patients with melanoma." (PMID 32841222, 2020). "Since IL-32 treatment mainly induced CCR5 ligands, we inoculated Ccr5-deficient (Ccr5–/–) mice with B16F10 melanomas." (PMID 32841222, 2020). "In line with the human data, the most salient feature of IL-32–treated B16F10 melanomas was a chemokine-rich TME, concomitant with enhanced frequencies of activated, tumor-specific CD8+ T cells, recapitulating the findings from human melanoma TCGA samples." (PMID 32841222, 2020). "For further analysis, we stratified melanoma samples from TCGA by IL-32 expression to delineate IL-32hi and IL-32lo groups (top and bottom 25%, respectively)." (PMID 32841222, 2020). "In this study, we demonstrate that IL-32 potentiates T cell infiltration into the tumor, leading to enhanced survival of patients with melanoma and response to ICB." (PMID 32841222, 2020).